DAO (D-amino acid oxidase)
Description:
Catalyzes the oxidative deamination of D-amino acids with broad substrate specificity. Required to catabolize D-amino acids synthesized endogenously, of gastrointestinal bacterial origin or obtained from the diet, and to use these as nutrients (By similarity). Regulates the level of D-amino acid neurotransmitters in the brain, such as D-serine, a co-agonist of N-methyl D-aspartate (NMDA) receptors, and may modulate synaptic transmission. Catalyzes the first step of the racemization of D-DOPA to L-DOPA, for possible use in an alternative dopamine biosynthesis pathway. Also catalyzes the first step of the chiral inversion of N(gamma)-nitro-D-arginine methyl ester (D-NNA) to its L-enantiomer L-NNA that acts as a nitric oxide synthase inhibitor (By similarity). The hydrogen peroxide produced in the reaction provides protection against microbial infection; it contributes to the oxidative killing activity of phagocytic leukocytes and protects against bacterial colonization of the small intestine (By similarity). Enzyme secreted into the lumen of the intestine may not be catalytically active and could instead be proteolytically cleaved into peptides with antimicrobial activity (By similarity). The hydrogen peroxide produced in the reaction may also play a role in promoting cellular senescence in response to DNA damage. Could act as a detoxifying agent which removes D-amino acids accumulated during aging.
Synonyms: DAAO; DAMOX; OXDA
Tractability: Small molecule: a structure with a bound ligand is known; a high-quality ligand is known; it has a high-quality binding pocket; it belongs to a druggable protein family. Antibody: UniProt places it where antibodies can reach, with high confidence; its Gene Ontology location is reachable by antibodies, with medium confidence. PROTAC: its protein half-life has been measured; a small molecule that binds it is known.
Target class: Enzyme; Oxidoreductase
Chemical probes: CHEMBL3613921
Gene: Protein-coding gene on chromosome 12 (108,858,932 to 108,901,051, forward strand). Ensembl gene ENSG00000110887.
Subcellular location: Peroxisome matrix; Cytoplasm, cytosol; Presynaptic active zone; Secreted
Pathways (Reactome):
Metabolism: Glyoxylate metabolism and glycine degradation
Protein localization: Peroxisomal protein import
Gene Ontology:
Molecular function: D-amino-acid oxidase activity; FAD binding; glycine oxidase activity; identical protein binding; protein binding; D-amino-acid dehydrogenase activity
Biological process: D-alanine catabolic process; D-amino acid catabolic process; D-serine biosynthetic process; D-serine catabolic process; dopamine biosynthetic process; L-proline catabolic process; digestion; neutrophil-mediated killing of gram-negative bacterium; amino acid catabolic process; antibacterial humoral response; D-amino acid metabolic process; L-amino acid catabolic process
Cellular component: cytoplasm; cytosol; extracellular region; mitochondrial outer membrane; peroxisomal matrix; presynaptic active zone
Genetic constraint (gnomAD): Loss-of-function variants: 44 observed, 46.29 expected, observed/expected ratio (o/e) 0.95, 90% interval 0.75 to 1.22. The upper end of that interval is the gene's LOEUF score, 1.22, which puts it in group 5 of 6, group 1 being the genes least tolerant of losing a copy. Missense variants: 430 observed, 452.94 expected, observed/expected ratio (o/e) 0.95, 90% interval 0.88 to 1.03. Synonymous variants: 155 observed, 171.75 expected, observed/expected ratio (o/e) 0.9, 90% interval 0.79 to 1.03.
Gene-disease validity (ClinGen):
ClinGen rates the evidence that DAO causes each of these diseases.
amyotrophic lateral sclerosis (autosomal dominant): Refuted. Amyotrophic lateral sclerosis (ALS) is a neurodegenerative disease characterized by progressive muscular paralysis reflecting degeneration of motor neurons in the primary motor cortex, corticospinal tracts, brainstem and spinal cord.
Homologues: Orthologues: chimpanzee DAO (98% identical), macaque DAO (95% identical), guinea pig DAO (86% identical), pig DAO (85% identical), mouse Dao (80% identical), rat Dao (80% identical), rabbit DAO (79% identical), dog DAO (76% identical), tropical clawed frog dao (62% identical), zebrafish dao.3 (61% identical), zebrafish dao.1 (59% identical), zebrafish dao.2 (59% identical), and 6 more. Paralogues in human: DDO (40% identical).
Diseases named in the same sentence as DAO in open-access papers:
DAO is named in the same sentence as 92 diseases in open-access papers, as found by Europe PMC text mining. Sharing a sentence is not in itself a finding about the gene and the disease. The quoted sentences say what the papers report.
schizophrenia (96 papers, 2007 to 2025). A major psychotic disorder characterized by abnormalities in the perception or expression of reality. "People carrying mutations in D-serine racemase and D-amino acid oxidase, as well as other enzymes involved in D-serine metabolism, are much more likely to have schizophrenia." (PMID 40427508, 2025). "Several studies indicate an association between DAO gene, its potential regulator G72, and schizophrenia." (PMID 35883465, 2022). "Although reports on the association of DAO and G72 with schizophrenia are ambiguous, these genes remain candidates in schizophrenia because of their roles in glutamatergic signaling, which has been associated with schizophrenia in multiple lines of research." (PMID 34658976, 2021). "Remarkably, an intriguing finding was that we further inferred the causal link between DAO and G72 protein levels in influencing schizophrenia disease status." (PMID 32582679, 2020). "In our analysis, there was a significant causal link involving DAO levels and G72 levels (P = 0.0036) in influencing schizophrenia disease status." (PMID 32582679, 2020). "To date, there is only limited evidence for disease associations of DAO (schizophrenia), RFLNA (spondylocarpotarsal synostosis), and EHHADH (Fanconi renotubular syndrome)." (PMID 31533369, 2019). "D-amino acid oxidase (DAO) is an enzyme that degrades amino acids, and its gene locus was found linked to schizophrenia along with several links to amyotrophic lateral sclerosis (ALS)." (PMID 31533369, 2019). "First of all, DAO-related genetic associations have been linked to the development of schizophrenia in multiple recent studies." (PMID 31547425, 2019). "Additional meta-analyses supported a genetic association between DAO, G72, and schizophrenia: they have been classified as schizophrenia susceptibility genes." (PMID 30547037, 2018). "The single nucleotide polymorphisms of genes related to D-serine synthesis and metabolism, such as genes encoding serine racemase (SR), D-Amino Acid Oxidase (DAAO), and the DAAO activator G72, are also associated with schizophrenia." (PMID 30459650, 2018). "The schizophrenia risk G-allele of DAO rs3918347 nominally increased risk for those UHR individuals with attenuated positive symptoms syndrome." (PMID 29326614, 2017). "Studies have demonstrated an association between schizophrenia and d-amino acid oxidase (DAO), DAO activator (DAOA)/G72, and neuregulin 1 (NRG1) single-nucleotide polymorphisms (SNPs)." (PMID 29326614, 2017). "We found that the schizophrenia risk G-allele of DAO rs3918347 had a tendency to be a risk allele for APSS compared to the remaining help-seeking group." (PMID 29326614, 2017). "The most recent report from the Psychiatric Genomics Consortium (PGC) didn’t reveal association between DAO gene and schizophrenia (odds ratio = 0.979, p = 0.65 for the SNP rs55944529 in CEU sample (Sweden 1–6))." (PMID 26986737, 2016). "In a later study, also elevated activity of DAO was linked to schizophrenia, corresponding to reduced D-serine levels and NMDA receptor hypoactivity." (PMID 26686055, 2016). "The tetra-nucleotide haplotype frequencies (HF) of the DAO gene and their associations with schizophrenia in the original and replicated samples." (PMID 26986737, 2016). "Most importantly, DAO shows genetic associations with human neurological diseases such as schizophrenia and amyotrophic lateral sclerosis (ALS), both of which essentially involve forebrain pathology." (PMID 24959138, 2014). "d-Ser was found to inhibit the AMPA receptor–mediated current in rat hippocampal neurons; thus, the DAO gene product was implicated in the pathogenesis of schizophrenia." (PMID 23555897, 2013). "This argument is consistent with the observations that polymorphisms of SR and DAO genes were implicated as risk factors for schizophrenia, respectively)." (PMID 23555897, 2013). "Our analysis shows that DAO plays an important role in the genetic associations and interactions for schizophrenia." (PMID 23555897, 2013).
schizophrenia (continued). "Several psychiatric diseases, including schizophrenia and bipolar disorder, are linked to overexpression of DAO and G72." (PMID 24362575, 2013). "Overexpression and hyperactivity of brain d-amino acid oxidase (DAO) have been associated with schizophrenia." (PMID 24362575, 2013). "The gene encoding G72, like that for DAO, is a susceptibility gene for schizophrenia and bipolar disorder." (PMID 24362575, 2013). "Genetic interaction analysis found that DAO is a master gene in the genetic interaction network underlying schizophrenia." (PMID 23555897, 2013). "Four single nucleotide polymorphisms (SNPs) within the D-amino acid oxidase (DAO) gene located at 12q24.11 have also been found to show allelic association with schizophrenia." (PMID 19586533, 2009). "This perhaps relates to DAO's candidacy as a putative schizophrenia susceptibility gene, as the associated polymorphisms are all non-coding and so the mechanism of association is probably through an effect on gene expression, as for other risk genes." (PMID 17880399, 2007). "Thus, an analysis of the DAO gene was performed, and four intronic SNPs were found to be associated with schizophrenia in a French-Canadian sample." (PMID 35883465, 2022). "Consistently, the DAO gene has been shown to be a susceptibility gene for schizophrenia and its neurocognitive deficits, suggesting that DAO inactivation could result in showing anti-schizophrenic effects." (PMID 35225861, 2022). "In relation to this, G72/G30, a modulator of DAO, has been implicated in schizophrenia." (PMID 35225861, 2022). "In addition, we identified a causal link between DAO and G72 protein levels in influencing schizophrenia disease status." (PMID 32582679, 2020). "In addition, we found that a significant causal link between DAO and G72 protein levels possessed a strong potential to reflect schizophrenia disease status." (PMID 32582679, 2020). "However, dysfunction of SRR, the d-serine degrading d-amino acid oxidase (DAO), and the main d-serine transporter alanine-serine-cysteine transporter 1 (Asc-1) are implicated in the development of schizophrenia, Alzheimer's disease, and depression." (PMID 30093356, 2018). "Although some aspects of DAAO-pLG72 interaction need further investigations, several meta-analyses have provided a moderate degree of support for a genetic association between G72, DAO, and schizophrenia, thus sketching them in the category of schizophrenia susceptibility genes." (PMID 29946548, 2018). "Therefore, aberrant DAO activity is implicated in the etiology of neuropsychiatric diseases, such as schizophrenia and amyotrophic lateral sclerosis." (PMID 29255714, 2017). "Additionally, a SNP coding for D-Amino Acid Oxidase enzyme involved in glutamatergic neurotransmission (DAAO), has been demonstrated to be associated with schizophrenia in case-control studies." (PMID 27895608, 2016). "Inhibiting DAO could therefore provide an effective and viable means of enhancing cognition, particularly in disorders like schizophrenia, in which NMDAR hypofunction is implicated." (PMID 26833794, 2016). "D-amino acid oxidase (DAO) has been reported to be associated with schizophrenia." (PMID 26986737, 2016). "We did find significant association of NRG1 and DAO genes with schizophrenia." (PMID 23555897, 2013). "However, a risk haplotype, namely A-T-C of the SNP triplet rsDAO7-rsDAO8-rsDAO13 of the DAO gene, was strongly associated with schizophrenia." (PMID 23555897, 2013). "Our sample size was too small to investigate whether any of the schizophrenia-associated DAO polymorphisms contributed to the elevated DAO expression seen here in the disorder." (PMID 17880399, 2007). "In the light of multiple scientific reports assessing and supporting the hypothesis of DAO alteration as a neurobiological hallmark of schizophrenia, novel chemical compounds targeting and suppressing the oxidase activity have been developed to ameliorate psychotic symptoms." (PMID 35883465, 2022).
schizophrenia (continued). "Consequently, DAO and serine racemase might be key enzymes for the association between D-amino acids and schizophrenia." (PMID 35225861, 2022). "Alternatively, a decrease in levels of NMDAR co-agonists (D-serine, glycine; for example due to genetic changes in the schizophrenia risk genes SR, DAO, or DAOA/G72) or increased levels of endogenous NMDAR blockers such as zinc or kynurenic acid, could play a role." (PMID 31824347, 2019). "The DAO gene was a susceptibility gene for schizophrenia and the genomic region between intron 1 and intron 8 may harbor functional genetic variants, which may influence the mRNA expression of DAO and neurocognitive functions in schizophrenia." (PMID 26986737, 2016). "The mechanism underlying the genetic association of DAO with schizophrenia remains unclear." (PMID 26986737, 2016). "As NMDA receptor hypofunction has been implicated in the pathophysiology of schizophrenia, the report of a functional interaction between G72 and DAO suggests a pathway whereby G72 could modulate DAO activity, D-serine levels and NMDA receptor activity and, thus, contribute to the disease pathology." (PMID 19077230, 2008). "On the other hand, sodium benzoate—an add-on treatment for treating schizophrenia—acts as an inhibitor of D-amino acid oxidase (DAAO), a peroxisomal flavoenzyme that is almost exclusively expressed within astrocytes, therefore increasing D-amino acid levels." (PMID 40427508, 2025). "In contrast to GlyT1 inhibitors, another promising therapeutic strategy for treating schizophrenia is to indirectly increase synaptic D-serine levels by targeting D-amino acid oxidase (DAAO)." (PMID 39408997, 2024). "In line with this idea, D-serine supplementation or treatment with DAO inhibitors significantly improved cognitive functions in animal models of aging, as well as in healthy subjects, PD, and schizophrenia patients." (PMID 38982054, 2024). "SNPs in the gene encoding G72, the activator of D-amino acid oxidase (DAO), were found to be associated with major psychiatric disorders, including schizophrenia." (PMID 37107350, 2023). "Sodium benzoate, a DAO inhibitor, has also improved several symptoms in chronic schizophrenia patients." (PMID 35225861, 2022). "Several studies have shown increased mRNA, protein, and/or enzymatic activity of DAO in post-mortem brain samples with schizophrenia." (PMID 35225861, 2022). "Other more selective DAO inhibitory drugs are currently tested in patients with schizophrenia and among these, luvadaxistat has shown a promising improvement in cognitive functions." (PMID 35883465, 2022). "In fact, DAO-related genetic alterations have been related to the development of schizophrenia, and DAO inactivation produces behavioral effects with potential therapeutic benefits." (PMID 35225861, 2022). "Imminent molecular work is required to further validate the contribution of G72/G30 and DAO to the pathogenesis of schizophrenia." (PMID 35225861, 2022). "The PPI is one of the principle forms of information processing measured in schizophrenia patients and rodents treated with DAO inhibitors or NMDA antagonists." (PMID 34575878, 2021). "Indirect GMS modulators, especially GlyT1 inhibitors and DAO inhibitors, open new avenues for the treatment of unmet medical needs for patients with schizophrenia." (PMID 34658976, 2021). "Enhanced DAO activity is considered a potential cause of reduced D-serine and subsequent impairment to NMDAR functioning in schizophrenia." (PMID 34658976, 2021). "In particular, compared with GlyT1 inhibitors, one of the promising approaches to the development of novel therapeutic compounds for treating schizophrenia is to indirectly increase synaptic D-serine levels by targeting DAO." (PMID 34658976, 2021). "Accumulating evidence from genetic studies has indicated that DAO and G72 are putative genes related to schizophrenia." (PMID 34658976, 2021).